NTSR1 (neurotensin receptor 1)
Diseases named in the same sentence as NTSR1 in open-access papers (continued):
Sharing a sentence is not in itself a finding about the gene and the disease.
Hyperglycemia (2 papers, 2008 to 2021). An increased concentration of glucose in the blood. "NTSR1 mediates the functions of neurotensin, e.g. hypotension, hyperglycemia, hypothermia, antinociception, and intestinal motility and secretion." (PMID 33627703, 2021). "Finally, the neurotensin receptor NTSR1 (P = 8.1×10−4) mediates hypotension, hyperglycemia, hypothermia, antinociception, and regulation of intestinal motility and secretion." (PMID 18670650, 2008).
melanoma (2 papers, 2020 to 2021). A malignant, usually aggressive tumor composed of atypical, neoplastic melanocytes. "The same study found that NT/NTSR1 activation is required for cell migration in the A375 melanoma cells." (PMID 32336282, 2020). "Inhibition of NTSR1 with SR48692 antagonist induced apoptosis in A375 melanoma cell line and reduced tumour growth in vivo." (PMID 32336282, 2020). "The authors suggested that NTSR1 may be a novel drug target in melanoma, however, there are no further studies to investigate its potential." (PMID 32336282, 2020).
neuroendocrine tumors (2 papers, 2015 to 2020). "Neurotensin (NTS), localized predominantly to the small bowel, stimulates the growth of a variety of cancers, including neuroendocrine tumors (NETs), mainly through its interaction with the high-affinity NTS receptor 1 (NTSR1)." (PMID 26298774, 2015).
pancreatic adenocarcinoma (2 papers, 2020 to 2024). "NTSR1 targeted radioligand therapy was given to 6 patients with advanced pancreatic adenocarcinoma resulting in partial remission in some cases." (PMID 32764278, 2020).
Sepsis (2 papers, 2024 to 2025). Sepsis is defined as life-threatening organ dysfunction caused by a dysregulated host response to infection. "In this study, we conducted differential gene expression and mendelian randomization (MR) analyses to target three regulated risk sepsis genes (core sepsis genes: LRPAP1, NTSR1, and SEMA4A)." (PMID 40756031, 2025). "We identified 307 highly expressed DEGs and 72 disease-related risk genes, culminating in the identification of three core sepsis genes including SEMA4A, LRPAP1, and NTSR1." (PMID 40756031, 2025). "This study proposes SEMA4A, LRPAP1, and NTSR1 as promising therapeutic targets for sepsis." (PMID 40756031, 2025). "Notably, the analysis highlighted LRPAP1, NTSR1, and SEMA4A as up-regulated risk genes in sepsis (core sepsis genes)." (PMID 40756031, 2025). "In sepsis, we found that Fluorouracil can decrease the expression of NTSR1." (PMID 38167131, 2024). "The results confirmed significantly higher expression levels of LRPAP1, NTSR1, and SEMA4A in these additional sepsis samples compared to the control group." (PMID 40756031, 2025). "Among three core sepsis genes, only SEMA4A was upregulated in the model group, whereas LRPAP1 and NTSR1 exhibited decreased expressions, contrary to previous results." (PMID 40756031, 2025). "This study offers a comprehensive analysis of genes contributing to sepsis by combining transcriptomics, MR, single-cell sequencing, and in vitro experiments, with a particular emphasis on SEMA4A, LRPAP1, and NTSR1." (PMID 40756031, 2025). "While the differential expression analysis of the dataset indicated that upregulation of NTSR1, LRPAP1, and SEMA4A in sepsis, our in vitro experiments revealed that only SEMA4A was upregulated in the model group." (PMID 40756031, 2025). "To gain deeper insights into the functions and pathways influenced by three core genes in sepsis, we conducted GO and KEGG enrichments among groups with high and low expression of NTSR1, LRPAP1, and SEMA4A genes." (PMID 40756031, 2025). "We identified significant upregulation of NTSR1, BCL6, ZDHHC19, MGLL, and ALPK1 in sepsis compared to healthy individuals, while VAV2 and SATB1 were significantly downregulated in sepsis." (PMID 38167131, 2024). "Additionally, correlation studies between core sepsis genes and immune cells unveil potential roles and regulatory effects of NTSR1, LRPAP1, and SEMA4A on immune cells in sepsis." (PMID 40756031, 2025). "The observed significant upregulation of NTSR1, BCL6, ZDHHC19, MGLL, and ALPK1 in sepsis compared to healthy individuals, along with the notable downregulation of VAV2 and SATB1 in sepsis, provides a comprehensive picture of the altered gene expression landscape during sepsis." (PMID 38167131, 2024). "Additionally, bulk RNA analysis revealed significant increases in NTSR1, BCL6, ZDHHC19, MGLL, and ALPK1 in sepsis, and significant decreases in VAV2 and SATB1 in sepsis; FCHO1 showed a significant decrease in sepsis patients who did not survive compared to those who survived at 28 days." (PMID 38167131, 2024).
anxiety disorder (1 paper, 2014). A category of psychiatric disorders which are characterized by anxious feelings or fear often accompanied by physical symptoms associated with anxiety. "Our results suggest the possibility that the DNA methylation of the promoter region of NTSR1 gene in AMY may induce a vulnerability to anxiety disorders, such as PTSD and phobia, as disturbances of the fear memory processes play an important role in the development of these diseases." (PMID 24831231, 2014).
autoimmune thyroiditis (1 paper, 2021). "The expression of NTSR1 was significantly lower compared to the increased expression of NPY1R in patients with hypothyroidism caused by autoimmune thyroiditis." (PMID 34104248, 2021). "The patients with hypothyroidism caused by autoimmune thyroiditis had considerably lower expression of NTSR1, while the expression of NPY1R increased." (PMID 34104248, 2021).
bone cancer (1 paper, 2018). A primary or metastatic malignant neoplasm affecting the bone or articular cartilage. "For bone cancer, we found that targeting protein NTSR1 is associated with drug sensitivity when the Hypoxia pathway is activated." (PMID 29844324, 2018).
brain infarct (1 paper, 2013). "The NT GPCRs usually mediate their action either directly as demonstrated for the protection of brain infarct against ischemia for NTSR1 or in combination with NTSR3/sortilin, as shown for the protective action of NT on pancreatic beta cells." (PMID 24709648, 2013).
breast adenocarcinoma (1 paper, 2014). "The systemic delivery of liposomal short-chain ceramide that targets NTSR1 limits solid tumor growth in syngeneic and athymic murine models of breast adenocarcinoma by inhibiting NTSR1 translocation into membrane microdomains, which ultimately inhibits the mitogen-activated protein kinase pathway." (PMID 24824754, 2014). "Thus, therapeutic approaches that inhibit expression and function of NTSR1 have proven successful on the human breast adenocarcinoma cell line MDA-MB-231, which has the TNBC phenotype." (PMID 24824754, 2014).
breast ductal carcinomas (1 paper, 2009). "In Chang's study, dealing with 24 breast ductal carcinomas classified according to the docetaxel response, NTSR1 was more intensively expressed in the group resistant to this chemotherapy agent." (PMID 19156213, 2009). "We previously demonstrated the presence of NTSR1 and NTS expression in breast ductal carcinomas, along with NTS induced effects on tumor growth, cellular mobility and collagen invasion of a cancer mammary cell line." (PMID 19156213, 2009).
carcinoid (1 paper, 2015). "To further delineate the possible proliferative effect of NTSR1, we used small interfering RNA (siRNA) against NTSR1 in BON cells, which express NTSR1 mRNA and have been widely utilized as a novel carcinoid cell model." (PMID 26298774, 2015). "In addition, we found that knockdown of NTSR1 decreased proliferation, expression levels of growth-related proteins, and anchorage-independent growth of BON human carcinoid cells." (PMID 26298774, 2015).
carcinoma in situ (1 paper, 2015). "Among noninvasive tumors, including precursor lesions and carcinoma in situ, levels of NTSR1 methylation were significantly higher in LST-G lesions than other morphological types, but histological type did not correlate with NTSR1 methylation." (PMID 26334593, 2015).
cocaine dependence (1 paper, 2024). A psychologically and socially impaired state, with or without physiological changes, that develops as a result of using cocaine and which leads to compulsive behaviors to acquire the substance. "This compound has been shown to reduce the side effects of NTSR1 agonists in the treatment of cocaine dependence." (PMID 38250036, 2024).
colitis (1 paper, 2020). Inflammation of the colon. "An increase in NT/NTSR1 mRNA was also detected in the mesenteric fat of mice with chemically induced colitis." (PMID 32429087, 2020). "According to the authors, NTSR1 expression might be responsible not only for early stages of CRC development but also for its progression and aggressive forms, as successive NTSR1 tissue expression increase was described from colitis, through dysplasia, to CRC itself." (PMID 32429087, 2020).
endometrial adenocarcinoma (1 paper, 2021). "Increased expression of NTSR1 mRNA was thought to be a result of a loss of NTSR1 promoter methylation in endometrial adenocarcinoma." (PMID 33034134, 2021).
Ewing sarcoma (1 paper, 2011). A small round cell tumor that lacks morphologic, immunohistochemical, and electron microscopic evidence of neuroectodermal differentiation. "High affinity NT binding sites have been found in various cancers, including Ewing's sarcoma and NTSR1 expression, driven by the Wnt/b-catenin pathway, is an early event in oncogenic transformation." (PMID 21364741, 2011).
gastric adenocarcinoma (1 paper, 2022). "Effects, underlying mechanisms, and clinical roles of NTSR1 on gastric adenocarcinoma cell proliferation and invasion." (PMID 36439693, 2022).
head and neck cancer (1 paper, 2014). A primary or metastatic malignant neoplasm affecting the head and neck. "Similarly, in head and neck cancers, patients with high NTS and NTSR1 expression had a higher rate of distant metastasis." (PMID 25249545, 2014).
hypothyroidism (1 paper, 2021). Abnormally low levels of thyroid hormone. "So, there was a decrease in the expression of NTSR1 both in the patients with increased levels of anti-Tg and anti-TPO autoantibodies in the serum and patients with hypothyroidism caused by AIT compared to the increased NTSR1 expression in the patients with postoperative hypothyroidism." (PMID 34104248, 2021). "Our research found that patients with postoperative hypothyroidism had a considerably increased expression of NPY1R, NTSR1, and NPY4R." (PMID 34104248, 2021). "Our research identified that patients with postoperative hypothyroidism had a considerably increased expression of NPY1R, NTSR1, and NPY4R." (PMID 34104248, 2021). "The results from the RT2 Profiler Neuropeptides and receptor pathway-focused gene expression analysis indicated that in Group 1, which includes patients with postoperative hypothyroidism, among anti-apoptotic genes, the expression of NPY1R and NTSR1 was increased by 3.0 and 3.7 times, respectively." (PMID 34104248, 2021).
ischemic stroke (1 paper, 2020). A stroke disorder caused by obstruction of blood flow to the brain, due to thrombotic (local blood clot formation) or embolic (due to a blood clot or other material traveling from another site) event. "In our previous studies, we developed a pharmacological hypothermia treatment using neurotensin receptor 1 (NTR1) agonists and demonstrated the brain protective effects against ischemic stroke, hemorrhage stroke, and traumatic brain injury (TBI)." (PMID 32010477, 2020).
leiomyoma (1 paper, 2023). A well-circumscribed benign smooth muscle neoplasm characterized by the presence of spindle cells with cigar-shaped nuclei, interlacing fascicles, and a whorled pattern. "Some authors have been interested in the presence of NTS/NTSR1 in the tissues of the human myometrium and leiomyoma and, more particularly, in women having hormonal treatment for in vitro fertilization (IVF)." (PMID 36902025, 2023).
malignant glioma (1 paper, 2015). A grade III or grade IV glioma arising from the central nervous system. "Our results highlighted that NTS promotes the proliferation and invasiveness of malignant glioma cells through NTSR1 and its downstream signaling molecules, leading to Erk1/2 phosphorylation." (PMID 25644759, 2015). "The role of the NTS/NTSR1/Erk1/2 signal axis in the proliferation and invasiveness of malignant glioma cells was tested in vitro." (PMID 25644759, 2015). "Because the NTS/NTSR1-induced transactivation of the EGFR signaling pathway may complicate EGFR-targeted therapies in malignant glioma." (PMID 25644759, 2015). "It would be very valuable to know whether the cooperative relationship between NTSR1 and EGFR system exists in malignant glioma, and what its underlying molecular mechanism is." (PMID 25644759, 2015). "However, the role of NTS and NTSR1 in malignant glioma has only rarely been reported." (PMID 25644759, 2015). "The proliferation and invasiveness of malignant glioma cells could be suppressed by inhibiting the interaction between NTS and NTSR1 in vitro." (PMID 25644759, 2015).
prostate tumour (1 paper, 2020). "Geer S and colleagues tested the uptake of Lu-177-labelled NTSR1 antagonists into a cumulative tumour dose of 1.25Gy/MBq, in prostate specific membrane antigen (PSMA) negative and NTSR1 positive prostate tumour-bearing nude mice." (PMID 32336282, 2020).
renal fibrosis (1 paper, 2023). A final common manifestation of a wide variety of chronic kidney diseases characterized by glomerulosclerosis and tubulointerstitial fibrosis. "We analyzed the gene expression in a variety of kidney diseases, and only in a murine model of renal fibrosis UUO, the expression of Ntsr1, which encodes the receptor for NTS, upregulated (LogFC = 4,2604 [GSE87212])." (PMID 37927592, 2023).
squamous carcinoma (1 paper, 2014). "On the contrary, NTSR1 staining in the squamous carcinoma cells was often localized at the membrane level." (PMID 25249545, 2014).
steatosis (1 paper, 2025). Increased lipid within the cytoplasm of cells. "Importantly, we show a direct effect of NTS on steatosis development and suggest that the NTS/NTSR1 signaling axis represent a novel therapeutic target for MASLD." (PMID 40287434, 2025).
triple-negative breast carcinoma (1 paper, 2022). An invasive breast carcinoma which is negative for expression of estrogen receptor (ER), progesterone receptor (PR), and human epidermal growth factor receptor 2 (HER2). "Therefore, it is interesting to explore the effects of NTSR1 mutation in triple-negative breast cancer cell lines on proliferation, migration, invasion, and the response to antagonist SR48692." (PMID 36294386, 2022). "Our results indicated that NTSR1 mutation might be a potential new target for the treatment of triple-negative breast cancer." (PMID 36294386, 2022).
tumor (65 papers, 2006 to 2026). "The overexpression of cytoplasmic neurotensin receptor 1 was associated with higher pT (pathological) stage and higher tumor grade, whereas the nuclear location was correlated with lower pT stage, low Elston and Ellis grade and estrogen receptor positivity." (PMID 41301028, 2025). "For example, increased NTSR1 expression was associated with increased tumour size and number of metastatic lymph nodes in breast invasive ductal cell carcinomas." (PMID 32764278, 2020). "Interactions between NTS and NTSR1 induce pro-oncogenic biological effects associated with neoplastic processes and tumor progression." (PMID 25249538, 2014). "High NTSR1 expression was associated with a larger tumor size (p<0.01), SBR grade 3 (p<0.05), the number of positive lymph nodes (p<0.05), and as a consequence it was also associated with chemotherapy (p<0.01)." (PMID 19156213, 2009). "Moreover, high NTSR1 expression was linked to a larger tumor size, a grade 3 tumor, or a larger number of positive lymph nodes, making high NTSR1 expression an independent prognosis marker." (PMID 39519199, 2024). "We observed NTSR1 mutation in both patients, which indicated that NTSR1 might be a potential candidate for tumor progression." (PMID 36294386, 2022). "Neurotensin acts as a growth-promoting factor in various cancers through neurotensin receptor 1, activating oncogenic pathways that support tumor growth, invasion, and survival." (PMID 41301028, 2025). "The xenotransplantion model of NTSR1-positive human HT-29 tumor-bearing nude mice is one of the most frequently used tumor models for the development of NTSR1 radioligands." (PMID 40574013, 2025). "The present work deals with the optimization of the radiosynthesis of [99mTc]1 and [99mTc]2 and their in vitro and in vivo evaluation by biodistribution and SPECT/CT imaging studies in NTSR1-positive HT-29 tumor-bearing mice." (PMID 40574013, 2025). "For tumor targeting, we imparted NTSmut, a ligand with strong binding affinity to neurotensin receptor 1 (NTSR1), onto the nanoparticles." (PMID 40133959, 2025). "The proliferation of tumor cells can be induced by the binding of neurotensin to NTSR1 via several signalling pathways, including the phospholipase C pathway." (PMID 38496894, 2024). "For instances, differentially methylated m6As in genes such as CENPF, WNT7B and NTSR1 between tumor and normal tissues were hypermethylated in S2 PDAC samples compared to S1 PDAC samples." (PMID 37816727, 2023). "This demonstrates in tumor cells an exchange from the NTSR1-high form to the NTSR1-low form that depends on MMPs activity." (PMID 36949141, 2023). "Nevertheless, the lower affinity was balanced by the ability of the molecule to internalize into tumor cells via NTSR1, a key factor for in vivo tumor visualization." (PMID 38003529, 2023). "In our study, the use of RNA-seq data as well as global proteomic data inferred MAP3K19 and NTSR1 for pan-cancer tumor purity, immune score, and stromal score." (PMID 36439693, 2022). "Nuclear imaging of NTSR1 allows for noninvasive assessment of the receptor levels of NTSR1 on the primary tumor, as well as potential metastases." (PMID 36559218, 2022). "Several (pre)clinical trials have been conducted evaluating the performance of NTSR1 targeted peptides for tumor-targeted PET/CT as well as NIR-fluorescence imaging." (PMID 34885196, 2021). "NTSR1 methylation values were characterized by a high variance, which suggested the existence of two subsets of tumor samples, one with increased and another one with decreased methylation compared to normal colon samples." (PMID 34680073, 2021). "On the contrary, when these cells were inoculated orthotopically into the pancreas of nude mice, we found that NTSR1 promoted primary tumor formation of SUIT‐2 cells significantly and Panc‐1 cells partially in vivo." (PMID 33034134, 2021).